CTLA4 (cytotoxic T-lymphocyte associated protein 4)
Diseases named in the same sentence as CTLA4 in open-access papers (continued):
Sharing a sentence is not in itself a finding about the gene and the disease.
Sepsis (continued). "Similarly, the observed lower 28-day mortality risk among CTLA-4 GG patients may be due to the less distinctive immunosuppressive component exhibited by these patients within 28 days after sepsis onset." (PMID 30310101, 2018). "Immune checkpoint proteins, such as PD-1 and CTLA-4, are upregulated in sepsis, leading to immunosuppression by inhibiting T cell activation and proliferation." (PMID 40129981, 2025). "Preclinical studies have demonstrated that blocking PD-1 or CTLA-4 can improve survival in sepsis models by enhancing T-cell responses, though overactivation of the immune system remains a concern." (PMID 40563999, 2025). "The Peptide Genomic Therapy with NTCI peptide reduced the elevated Ctla4 gene expression by almost 5-fold during the polymicrobial sepsis." (PMID 41229427, 2025). "The CD15+CD14+ monocytes and CD45RA−CX3CR1+CTLA4+CD4+ T cells were only significantly increased in children with sepsis in those >1 year of age." (PMID 40433376, 2025). "We emphasize that the remarkable 21-fold increase of Ctla4 gene in the spleen during sepsis explains the immunosuppressive stage of this life-threatening complication." (PMID 41229427, 2025). "Consistently, clinical studies further show that an elevated proportion of CTLA-4+ Tregs positively correlates with sepsis severity." (PMID 40806563, 2025). "The NTCI peptide-induced downregulation of the Ctla4 gene prevented its immunosuppressive action in polymicrobial sepsis." (PMID 41229427, 2025). "Fifth, the prominent role of CTLA4 in immunosuppressive stage of sepsis and its reversal by the PGT with NTCI peptide." (PMID 41229427, 2025). "The expression of CTLA-4 on CD4+ T cells of sepsis patients is significantly increased, suggesting it as a potential therapeutic target." (PMID 41209006, 2025). "There was a progressive increase in the frequency of the CD15+CD14+ monocytes, CD45RA−17A+CD4+ T cells, and CD45RA-CX3CR1+CTLA4+CD4+ T-cell subsets from control to sepsis with organ dysfunction." (PMID 40433376, 2025). "In humans, sepsis also leads to an upregulation of PD-1 and CTLA-4 on T cells compared to healthy controls." (PMID 41142792, 2025). "Pre-clinical studies demonstrated that treatment with anti-CTLA-4 antibody maintains effector T cell function and improves sepsis survival outcomes." (PMID 39372401, 2024). "Enhanced CTLA-4 expression occurs more frequently in patients with sepsis, and blocking CTLA-4 improved survival in experimental bacterial and fungal sepsis." (PMID 39104530, 2024). "Additionally, we further exploited the associated regulatory pathways of CTLA4 accumulation in sepsis, and it was found that there was a close relationship between the mTOR signaling pathway, autophagy, and CTLA4 accumulation, and elucidated the mTOR-autophagy-CTLA4 regulatory axis." (PMID 39104632, 2024). "As numerous studies have proved the regulation of T cell proliferation, activation, and related function are fundamental signals delivered by CTLA4, and its role in sepsis naturally cannot be ignored." (PMID 39104632, 2024). "The most documented was immuno-adjuvant therapy with anti-PD-1, anti-CTLA-4, and anti-Tim-3 antibodies, which can reverse sepsis-induced immunosuppression and improve survival in sepsis." (PMID 39072327, 2024). "From this, combined with the data showing that alcohol-drinking septic mice exhibit increased CTLA-4 expression on Treg compared with water-drinking septic mice, we infer that blocking CTLA-4 reduces Treg function and improves immune competence during sepsis." (PMID 38226924, 2024). "In order to elucidate the function of CTLA4 in CD4+ T cell dysfunction during sepsis, we employed western blotting to quantify CTLA4 expression, which revealed that CTLA4 was considerably accumulated in septic mice." (PMID 39104632, 2024).
Sepsis (continued). "Our data show that under conditions in which CTLA-4 is blocked, during which Treg proliferation is increased but suppressive function is inhibited, sepsis survival of alcohol-drinking mice is improved." (PMID 38226924, 2024). "CTLA-4+ Treg (CD3+CD4+CD25+CD127-FOXP3+CTLA-4+) frequencies and CTLA-4 expression were significantly higher in neonates with clinical sepsis compared to healthy subjects with prenatal risk factors." (PMID 39072327, 2024). "Our data show that deletion of CTLA-4 results in increased activated eTreg in the setting of sepsis." (PMID 38226924, 2024). "Considering the regulatory role of CTLA4 on T cells and its lysosomal degradation pathway, we wanted to know the role of autophagy in CTLA4 function in sepsis." (PMID 39104632, 2024). "In line with previous studies, it was demonstrated that CTLA-4 expression is upregulated on CD4+ in sepsis." (PMID 39104632, 2024). "Although anti-CTLA-4 antibody was already available, few reports or studies illustrated its effect on sepsis and SAI." (PMID 39104530, 2024). "We sought to characterize the role of CTLA-4 during sepsis in the setting of chronic alcohol exposure using a murine model of chronic alcohol ingestion followed by cecal ligation and puncture." (PMID 38226924, 2024). "Cytotoxic T lymphocyte antigen 4 (CTLA-4) is a crucial immune checkpoint receptor that inhibits the activation and proliferation of T cell in sepsis." (PMID 39372401, 2024). "Future experiments to determine the impact of CTLA-4 blockade on the function and trafficking of both Treg and Tconv in the context of alcohol and sepsis will be beneficial in this regard." (PMID 38226924, 2024). "In the cord blood of newborns developing sepsis, we observed higher frequencies of CTLA-4+ and PD-1+ Treg." (PMID 39072327, 2024). "The AUC of CTLA-4 MFI for the prediction of 28-day mortality of all sepsis patients was 0.906, which was better than those for lymphocyte and CD4+ T lymphocyte counts (AUC: 0.650 and 0.693." (PMID 39104530, 2024). "We analyzed the immune targets of immune-related drugs to predict their potential use in sepsis and showed that nine target loci (CSF2RA/B, CSF3R, IFNGR1/2, IL7R, PDL1, CTLA4, and LAG3) differed in the high-/low-risk block." (PMID 36389695, 2022). "Some research has observed that soluble BTLA and TIM-3, like PD-1 and CTLA-4, is elevated in sepsis patients." (PMID 35958579, 2022). "Another study showed that CTLA-4, a molecule in immune cytotoxic lymphocytes, is up-regulated in sepsis, which can promote the occurrence of immunosuppression and eventually increase mortality." (PMID 36532072, 2022). "PD-1, CTLA-4, and their ligands, have been shown to be upregulated on T cells during sepsis, which has led to investigations on immune checkpoint inhibition also as immunomodulatory treatment in infections." (PMID 35312715, 2022). "Since the early septic immune hyporesponsiveness appears to be unresponsive to PD1/L1 or CTLA4 inhibition, however, our findings question the potential use of checkpoint inhibitory treatments during early sepsis." (PMID 35981050, 2022). "The expression of CTLA-4 on CD4+ T cells in patients with sepsis is significantly increased, suggesting that CTLA-4 is a potential target for sepsis treatment." (PMID 36209190, 2022). "CTLA-4 antibody treatment attenuates sepsis-induced apoptosis and improves survival in a CLP sepsis model." (PMID 36209190, 2022). "In an initial phase of sepsis, this mouse model present a higher expression of IL-10 and CTLA-4 in Tregs, reduced tissue damage and promotion of macrophage polarization to an M2 phenotype induced by sepsis via Tregs." (PMID 35370925, 2022). "VISTA was abundantly expressed at the early stage of sepsis, differing from other B7 family ligands, such as PD-1 and CTLA-4." (PMID 34366711, 2021).
Sepsis (continued). "Recently, animal studies demonstrated that blockade of the CTLA-4 or PD-1/PD-L1 pathway improved survival in several clinically relevant models of sepsis, which highlighted the significant degree of coinhibitory molecules in sepsis-induced immune dysfunction." (PMID 34366711, 2021). "Among the immune checkpoint inhibitors, PD-1/PD-L1 and CTLA-4 inhibitors significantly improved survival and clinical manifestation in preclinical models of sepsis, which lead to their testing in a human clinical trial of severe sepsis." (PMID 34638546, 2021). "Emerging evidence suggests that negative costimulatory immunoregulatory checkpoint proteins such as PD-1 or CTLA-4 play a key role in the regulation of pro- and anti-inflammatory pathways in the clinical syndrome of sepsis." (PMID 34830585, 2021). "In particular, genetic variants in key genes of the host immune response, including programmed cell death protein 1 (PD-1) and cytotoxic T-lymphocyte associated protein 4 (CTLA-4) inter alia, have been studied in patients experiencing sepsis." (PMID 33171904, 2020). "Coinhibitory immune checkpoint proteins, such as PD-1 and CTLA-4, have been reported to play key roles in the course of sepsis, and our working group has revealed genetic associations of their genes with the survival of septic patients." (PMID 30634576, 2019). "Considering the complexity of the immune response in sepsis, it is important to examine factors involved in the activation and upregulation of the immune system, such as the coinhibitory checkpoint protein CTLA-4." (PMID 30310101, 2018). "Average SOFA and organ-specific SOFA scores from the first 28 days after sepsis onset (unless previously dismissed or deceased) were compared between the CTLA-4 rs231775 genotypes." (PMID 30310101, 2018). "Post-mortem studies of patients dying of sepsis has demonstrated elevations in co-inhibitory receptors PD-1 and CTLA-4 in splenic T cells, while the ligand PD-L1 was elevated in antigen presenting cells and tissue macrophages." (PMID 30459764, 2018). "In conclusion, our study provides the first evidence for CTLA-4 rs231775 as a prognostic variable for the survival of Caucasian patients with sepsis." (PMID 30310101, 2018). "Similar to the effect of sera from ALF patients, we report an elevation in CTLA4 expression after exposure to sera from sepsis patients." (PMID 28363639, 2017). "Anti-CTLA-4 at a low dose (33 μg per mouse) also improves survival in a two hit model of sepsis, comprised of slowly progressive CLP-induced sepsis followed by infection with a fungus, Candida albicans." (PMID 29135922, 2017). "While increased PD-1 expression on T cells is an established marker of immunoparalysis in sepsis, the roles of CTLA-4 and BTLA remain to be determined." (PMID 28056053, 2017). "For example, in murine model of CLP sepsis, anti-CTLA-4 antibody has been shown to be detrimental at higher doses." (PMID 29135922, 2017). "A prospective clinical study showed that as sepsis progressed, CTLA-4 expression was increased at day 7 on circulating T lymphocytes, as compared to the expression levels at the onset of sepsis." (PMID 29135922, 2017). "Experimental models have demonstrated that blockade of the PD-1 and CTLA-4 pathways can improve outcome in sepsis." (PMID 28056053, 2017). "In peripheral blood, sepsis induced a significant increase of PD-1 and CTLA-4 expression in CD4+ T cells in young and aged mice." (PMID 24962182, 2014). "Enhanced CTLA-4 expression was demonstrated more frequently in patients with sepsis than in non-infected critically ill patients or control subjects, and blocking CTLA-4 improved survival in bacterial and fungal experimental sepsis." (PMID 24886820, 2014). "• Programmed cell death-1 (PD-1), programmed cell death ligand-1 (PD-L1) and cytotoxic T-lymphocyte antigen-4 (CTLA-4), are important inhibitors of immune cell function which have be shown to be increased in patients with sepsis." (PMID 23663657, 2013).
Sepsis (continued). "Regulatory Treg expansion in sepsis is marked by a highly suppressive phenotype defined by CD25^high and FoxP3+ expression, together with upregulation of inhibitory molecules including cytotoxic T lymphocyte–associated protein 4 (CTLA-4) and PD-1." (PMID 41007702, 2025). "Immune checkpoint inhibitors, such as anti-PD-1 (e.g., pembrolizumab) and anti-CTLA-4 (e.g., ipilimumab) antibodies, have revolutionized cancer treatment by reactivating antitumor immunity and are now being explored in sepsis to reverse immune paralysis and restore immune function." (PMID 40563999, 2025). "Notably, blockade of PD-1 or CTLA-4 has demonstrated efficacy in restoring T cell function and improving survival in preclinical sepsis models." (PMID 41007702, 2025). "Anti-inflammatory therapies, such as IL-6 and TNF-α inhibitors, show promise in mitigating inflammation, while immune checkpoint inhibitors like anti-PD-1 and anti-CTLA-4 antibodies are being explored to restore immune function in sepsis and enhance antitumor immunity in cancer." (PMID 40563999, 2025). "In negative regulation, inhibitory receptors such as CTLA4 and PD-1 play a particularly significant role and have become key targets of anti-tumor therapy, which could be useful in sepsis treatment." (PMID 40504881, 2025). "To further determine the discriminatory ability of CTLA-4 for the incidence of immunosuppression in patients with sepsis, we generated ROC curves, and found that CTLA-4 MFI was better than the other parameters, with an area under the curve (AUC) value of 0.945." (PMID 39104530, 2024). "In our study, based on the overall immune environment in sepsis, we first explored the effect of mTOR regulation of CTLA4 on overall CD4+ T-cell function, and further experiments and discussions are needed in the future on the function of different cell subtypes, such as Treg cells, Th17." (PMID 39104632, 2024). "The current predicament for SAI treatment requires us to have a deeper understanding of the regulation mechanism of CTLA-4 and find more appropriate intervention sites, so as to achieve the most appropriate immune regulation of patients with sepsis and patients with SAI." (PMID 39104530, 2024). "Then, we could draw a conclusion that mTOR deletion restore CD4+ T-cell dysfunction in sepsis through alleviating CTLA4 accumulation by easing autophagy disorder." (PMID 39104632, 2024). "It is intriguing to investigate whether lactate modulates CTLA-4 expression in Treg cells, potentially impairing immune responses in sepsis." (PMID 39372401, 2024). "We finally provide that mTOR may be a potential target for sepsis treatment by alleviating autophagy disorder to reduce CTLA4 accumulation." (PMID 39104632, 2024). "Consistent with this, Pearson’s analysis identified that CTLA-4 overexpression significantly correlated with LC3II expression in patients with sepsis (R2 = 0.688, P<0.0001), patients with SAI (R2 = 0.678, P<0.0001), and non-surviving patients with SAI (R2 = 0.724, P=0.002)." (PMID 39104530, 2024). "CTLA-4+ Treg frequencies were not different among healthy newborns (with or without perinatal risk factors) and neonates with presumed sepsis." (PMID 39072327, 2024). "The aim of this study was to clarify the relationship between expression level of CTLA-4 on CD4+ T cells and sepsis-associated immunosuppression (SAI), and to elucidate the possible mechanism of mTOR pathway mediated autophagic-lysosomal disorder in regulating CTLA-4 expression." (PMID 39104530, 2024). "We initially targeted CTLA-4 for checkpoint inhibition given data suggesting that this can facilitate a proinflammatory response to compensate for the relative immunoparalysis conferred by coinhibitory markers during sepsis." (PMID 38226924, 2024).
Sepsis (continued). "To test and explore the viability of targeting mTOR to regulate CD4+ T-cell autophagy in sepsis as a way to minimize CTLA4 accumulation and hence alleviate CD4+ T-cell dysfunction, we employed rapamycin, a particular mTOR inhibitor, to corroborate the genetic approach's results." (PMID 39104632, 2024). "Therefore, we designed this experiment to explore the relationship between mTOR, autophagy, and CTLA4 in sepsis, the mechanism related was shown in the graphical abstract." (PMID 39104632, 2024). "Therefore, the inhibitory molecules PD-1 and CTLA-4 play a crucial role in the immunosuppressive phase of sepsis." (PMID 39072327, 2024). "Drawing from two distinct knockout models, namely T-cell-specific TSC1 knockout (TSC1-KO) mice and T-cell-specific mTOR knockout (mTOR-KO) mice, we investigated the mTOR pathway's regulatory function on the autophagy level of CD4+ T cells and CTLA4 accumulation in sepsis." (PMID 39104632, 2024). "However, in mice chronically exposed to alcohol, administration of anti–CTLA-4 mAb after sepsis induction conferred a significant survival advantage versus untreated alcohol-drinking controls." (PMID 38226924, 2024). "Intervention strategies, such as anti-programmed cell death (PD)-1/PD-L1 mAb, blocking cytotoxic T lymphocyte antigen (CTLA)-4, and blocking 2B4, have improved survival in experimental models of sepsis and recent clinical trials through improved T cell-induced immunosuppression." (PMID 35281010, 2022). "Mechanically, A2aR inactivation was associated with decreased frequencies and reduced function of Foxp3+ Tregs, as evidenced by Foxp3 and CTLA-4 expression and classical effector T-cell proliferative assays, suggesting Treg modulation is a potential protective mechanism against sepsis." (PMID 36148230, 2022). "PD-1 and CTLA-4 were also a co-suppressor involved in T cell suppression in sepsis." (PMID 36518755, 2022). "The absolute number of CD4+TIM-3+, CD4+PD-1+, and CD4+CTLA-4+ T cells were positively correlated with the severity of sepsis, especially CD4+PD-1+ T cells, which may be a risk factor for sepsis." (PMID 35281010, 2022). "Indeed, blockade of PD-1/PD-L1 or CTLA-4 augmented the T cell functions in chronic virus infections, cancer, and clinically relevant models of sepsis." (PMID 34366711, 2021). "However, the significance of these specific CTLA-4 SNPs in regulating T cell function during sepsis remains to be explored, and hold significant potential for future research in personalized medicine approach." (PMID 33613563, 2020). "Limited studies have evaluated the role of CTLA-4 pathway during sepsis." (PMID 33613563, 2020). "In conclusion, our study provides the first evidence for CTLA-4 rs231775 as a prognostic variable for the survival of patients with sepsis and emphasizes the need for further research to reveal potential functional associations between CTLA-4 and the immune pathophysiology of sepsis." (PMID 30310101, 2018). "The GG genotype remained a significant covariate for 90-day mortality risk (hazard ratio: 0.624; 95% CI: 0.399-0,975; p = 0.03858), indicating that despite potential confounders, the CTLA-4 rs231775 GG genotype is an independent prognostic variable for survival of patients with sepsis." (PMID 30310101, 2018). "In murine models of sepsis, CTLA4 was also reported to be elevated on CD4+ and CD8+ T cells." (PMID 28363639, 2017). "As compared to PD-1–PD-L1 there are limited studies addressing the role of CTLA-4 during sepsis." (PMID 29135922, 2017). "T-lymphocytes from patients in the acute phase of sepsis accumulate genuine inhibitory cell surface co-receptors such as CTLA-4 or PD-1, providing one rationale explanation for the impaired functional responses to antigen and arguing for a T-cell-intrinsic origin of the observed immune paralysis." (PMID 25541945, 2014).